TAGLN2 (transgelin 2)
Synonyms: KIAA0120; HA1756
Tractability: Antibody: its Gene Ontology location is reachable by antibodies, with high confidence. PROTAC: UniProt records ubiquitination sites on it; ubiquitination databases record sites on it; its protein half-life has been measured.
Gene: Protein-coding gene on chromosome 1 (159,918,107 to 159,925,525, reverse strand). Ensembl gene ENSG00000158710.
Subcellular location (Human Protein Atlas): Cytosol; Actin filaments; Basal body; Vesicles
Pathways (Reactome):
Hemostasis: Platelet degranulation
Gene Ontology:
Molecular function: cadherin binding; protein binding; actin filament binding
Biological process: epithelial cell differentiation; actin filament organization
Cellular component: extracellular exosome; vesicle; actin cytoskeleton; cytosol; extracellular region
Genetic constraint (gnomAD): Loss-of-function variants: 14 observed, 26.04 expected, observed/expected ratio (o/e) 0.54, 90% interval 0.35 to 0.84. The synonymous counts are far from expectation, so gnomAD's model fits this gene poorly and the ratio says little. Missense variants: 208 observed, 269.08 expected, observed/expected ratio (o/e) 0.77, 90% interval 0.69 to 0.87. Synonymous variants: 77 observed, 103.86 expected, observed/expected ratio (o/e) 0.74, 90% interval 0.62 to 0.9.
Homologues: Orthologues: chimpanzee TAGLN2 (100% identical), macaque TAGLN2 (100% identical), dog TAGLN2 (99% identical), pig TAGLN2 (99% identical), guinea pig TAGLN2 (98% identical), mouse Tagln2 (96% identical), rabbit TAGLN2 (74% identical), rat Tagln2 (73% identical), Drosophila melanogaster Chd64 (42% identical), Caenorhabditis elegans cpn-2 (39% identical), Caenorhabditis elegans cpn-1 (37% identical), Drosophila melanogaster Mp20 (35% identical), and 2 more. Paralogues in human: TAGLN3 (69% identical), TAGLN (65% identical), CNN3 (45% identical), CNN1 (43% identical), CNN2 (43% identical).
Diseases named in the same sentence as TAGLN2 in open-access papers:
TAGLN2 is named in the same sentence as 99 diseases in open-access papers, as found by Europe PMC text mining. Sharing a sentence is not in itself a finding about the gene and the disease. The quoted sentences say what the papers report.
glioma (23 papers, 2017 to 2025). A benign or malignant brain and spinal cord tumor that arises from glial cells (astrocytes, oligodendrocytes, ependymal cells). "Using the glioma endothelial cell line U87 it was found that succinylated TAGLN2 recruits and represses the function of thymosin beta 4 X-linked, an inhibitor of actin polymerisation, to initiate cytoskeletal remodelling and glioma migration." (PMID 38213532, 2023). "For example, TAGLN2 (Transgelin-2), a member of the calponin family of actin-bundling proteins, has been reported to promote the development of glioma, and high TAGLN2 expression is associated with poor prognosis." (PMID 31803233, 2019). "Our analyses showed that not only was TAGLN2 expressed at significantly higher levels in GBMs compared to LGGs, but TAGLN2 was found to be significantly associated with glioma grade (p< 0.0001)." (PMID 30647847, 2018). "Increased TAGLN2 expression was associated with increasing tumor grade (P < 0.001), the mesenchymal molecular glioma subtype and worse prognosis in patients (P < 0.001)." (PMID 29110682, 2017). "We demonstrated that increased TAGLN2 expression levels were associated with higher tumor grade in human gliomas, and thus the mesenchymal molecular GBM subtype and unfavorable prognosis." (PMID 29110682, 2017). "Taken together, these results indicated that loss of TAGLN2 suppressed cell cycle progression and induced apoptosis in glioma cells." (PMID 29110682, 2017). "High TAGLN2 expression was associated with the mesenchymal molecular phenotype in human gliomas and thus poor prognosis in glioma patients." (PMID 29110682, 2017). "Importantly, it has been verified that TAGLN2 is high expressed in glioma tissues and is closely associated with tumor grade and prognosis in patients." (PMID 35505656, 2022). "Besides, activation of TAGLN2/PI3K/Akt signaling pathway in glioma was also detected to expound the underlying molecular mechanism." (PMID 35505656, 2022). "Since invasion into the surrounding brain parenchyma is a hallmark of gliomas and GBMs that contributes to local recurrence and worse prognosis, we assessed whether TAGLN2 is involved in invasion by glioma cells." (PMID 30647847, 2018). "Among them, RGS16, CLEC5A and TAGLN2 are key regulatory factors that promote glioma progression by activating the PI3K‐AKT pathway in gliomas." (PMID 38809929, 2024). "TAGLN2 overexpression, an actin-binding protein, significantly promotes the proliferation and relocation of glioma cells." (PMID 39707577, 2024). "In glioma tissue, hypersuccinylation of TAGLN2 seemed to play a critical role in promoting migration and angiogenesis." (PMID 38213532, 2023). "Consistent with the previous studies, the present research also confirmed that inhibition of TAGLN2/PI3K/Akt pathway potentiated the suppressive effect of Sal A on TMZ resistance in glioma cells." (PMID 35505656, 2022). "Dose-dependently decreased expressions of TAGLN2, p-PI3K and p-Akt in Sal A-treated U87 cells suggested that Sal A treatment inactivated TAGLN2/PI3K/Akt pathway in glioma cells." (PMID 35505656, 2022). "This work devoted to excavate the predictive values of Sal A and TAGLN2/PI3K/Akt signaling pathway in glioma treatment and to provide references for rational use clinically." (PMID 35505656, 2022). "Sal A treatment strengthened the suppressing effect of TMZ on glioma cell proliferation and reinforced the promoting effect of TMZ on glioma cell apoptosis, which were abolished by upregulation of TAGLN2." (PMID 35505656, 2022). "According to a previous study, TAGLN2 silencing specifically inhibits F-actin-rich compartments in glioma cells, thereby reducing the formation of pseudopodia during cell invasion." (PMID 34530821, 2021). "In gliomas, TAGLN2 is a potential oncogenic factor, which is regulated by TGFβ2 to promote glioma invasion and growth." (PMID 34093830, 2021).
glioma (continued). "These investigations were in accordance with our results that TAGLN2 has increasing expression in severe glioma (GBM) patients and worse tumor-hypoxic condition." (PMID 34446747, 2021). "TAGLN2 overexpression significantly increased the number of invading cells by approximately 2.5 to three-fold in glioma cells (p<0.05)." (PMID 30647847, 2018). "In summary, we have shown that TAGLN2 expression is silenced by promoter hypermethylation and therefore likely involved in the glioma hypermethylator phenotype of IDH1/2 mutant gliomas." (PMID 30647847, 2018). "This differential expression of TAGLN2 was primarily due to promoter hypermethylation in IDH1/2 mutant gliomas, suggesting involvement of TAGLN2 in the G-CIMP." (PMID 30647847, 2018). "We also found higher mRNA expression of TAGLN2 in GBM compared to IDH1/2 WT gliomas of lower grades." (PMID 30647847, 2018). "Our analyses identified TAGLN2 as one of the significantly up-regulated genes in IDH1/2 WT compared to IDH1/2 mutant low(er) grade gliomas." (PMID 30647847, 2018). "Our global methylation analysis of low(er) grade gliomas from our institutional cohort showed that CpG sites corresponding to the TAGLN2 promoter are more highly methylated in IDH1/2 mutant compared to IDH1/2 WT gliomas." (PMID 30647847, 2018). "While our study is limited by the availability of only one established heterozygous IDH1 mutant glioma cell line, the epigenetic regulation of transgelin, a homologue of TAGLN2, has been reported in multiple other cancer types." (PMID 30647847, 2018). "The TCGA analysis confirmed our previous results that increased TAGLN2 expression was significantly associated with IDH1/2 WT and higher grade gliomas." (PMID 30647847, 2018). "Since TAGLN2 has been shown to be a poor prognostic biomarker in other cancers and may play a role in glioma progression, we determined whether TAGLN2 expression was associated with overall survival (OS) of patients in both institutional and TCGA glioma cohorts." (PMID 30647847, 2018). "In order to confirm that this correlation was not due to the association between grade and IDH1/2 status, we also evaluated TAGLN2 mRNA levels in IDH1/2 WT gliomas of all grades." (PMID 30647847, 2018). "Glioma cells were transduced with lentiviral constructs expressing TAGLN2-targeting shRNA or control shRNA." (PMID 29110682, 2017). "The prognostic value of TAGLN2 expression in overall survival (OS) of glioma patients was examined in Kaplan-Meier survival curves." (PMID 29110682, 2017). "TAGLN2 knockdown in glioma cells induced cell cycle arrest at G0-G1 and cell apoptosis, and reduced growth in orthotopic xenografts." (PMID 29110682, 2017). "Knockdown experiments highlighted the function of TAGLN2 in promoting glioma cell invasion, the EMT phenotype, and tumor growth." (PMID 29110682, 2017). "Protein levels of TAGLN2 were also examined by immunohistochemistry in an independent cohort of human gliomas (n = 46) and normal brain tissues (n = 5) from Qilu Hospital (Jinan, China)." (PMID 29110682, 2017). "Here, we used publicly available datasets to determine the pattern of TAGLN2 expression in human gliomas, and its relationship with tumor grade, and other clinicopathological indicators and molecular features of gliomas." (PMID 29110682, 2017). "The TGFβ type I receptor specific inhibitor SB431542 prevented TAGLN2 induction, and therefore further supported a role for TGFβ2/Smad signaling in the regulation of TAGLN2 in glioma." (PMID 29110682, 2017). "Using immunofluorescence staining, we observed F-actin cytoskeletal changes induced by TAGLN2 depletion in gliomas." (PMID 29110682, 2017). "Based on its potentially crucial role in promoting glioma development, we were also interested in identifying upstream regulators of TAGLN2 expression." (PMID 29110682, 2017). "TAGLN2 silencing appeared to specifically suppress the F-actin-rich leading edge in glioma cells, thus reducing the formation of invadopodia during cell invasion." (PMID 29110682, 2017).
glioma (continued). "Here, we observed that TAGLN2 depletion significantly decreased glioma cell invasiveness and reversed EMT features, including changes in epithelial (E-cadherin) and mesenchymal markers (N-cadherin, Snail, Slug, Twist) in glioma cells." (PMID 29110682, 2017). "In addition, succinylation-mimicking and desuccinylation mutants were constructed, and functional experiments (proliferation, migration, and angiogenesis analysis) confirmed the pro-glioma angiogenesis and pro-tumor growth effects of TAGLN2 K40succ." (PMID 41189171, 2025). "Furthermore, the hypersuccinylation of TAGLN2 at K40 also markedly promoted glioma angiogenesis and destroyed the integrity of GECs; this subsequently facilitated the migration of glioma cells, correlating with poor prognosis in patients with glioma." (PMID 38315203, 2024). "Interestingly, TAGLN2 was detected with 15.36-fold higher Ksuc at K40 in glioma endothelial cells (GECs) than in normal endothelial cells (NECs), significantly promoting the adhesion and metastasis of GECs." (PMID 38315203, 2024). "Furthermore, the TAGLN2 Ksuc level in GECs is 15.36-fold higher than in NECs, thus promoting angiogenesis in glioma." (PMID 38315203, 2024). "Besides, silencing of TAGLN2 can markedly repress the growth and invasion of glioma in vitro and in vivo." (PMID 35505656, 2022). "Silence of TAGLN2 in gliomas cell lines significantly inhibited invasion and tumor growth." (PMID 33123464, 2020). "TAGLN2 therefore appears to regulate glioma invasion at multiple levels." (PMID 30647847, 2018). "Other clinical-pathologic factors known to be associated with IDH1/2 WT gliomas, such as 1p/19q non-codeletion status, astrocytoma histology and older age, were also identified to significantly correlate with TAGLN2 expression in the TCGA analysis." (PMID 30647847, 2018). "Moreover, we have shown that TAGLN2 is highly expressed in IDH1/2 WT gliomas and GBMs and appears to function as an oncogene." (PMID 30647847, 2018). "Our results also suggest that TAGLN2 may be involved in progression due to higher expression in glioblastomas compared to IDH1/2 WT gliomas of lower grades." (PMID 30647847, 2018). "An in-depth understanding of the role and regulation of TAGLN2 in gliomas may be useful in identifying novel therapeutic vulnerabilities in TAGLN2-associated signaling pathways driving proliferation, invasion and therapeutic resistance mechanisms in gliomas." (PMID 30647847, 2018). "Thus, it remains to be elucidated how the IDH1/2 mutant-generated oncometabolite, 2-HG, regulates the expression of TAGLN2 and how TAGLN2 in turn drives glioma cell proliferation and invasion." (PMID 30647847, 2018). "Subsequently, we tested the hypothesis that increased TAGLN2 expression may contribute to worse prognoses in IDH1/2 WT gliomas by investigating the role and regulation of TAGLN2 regulation in both LGGs and GBMs." (PMID 30647847, 2018). "TAGLN2 has also been shown to be dysregulated in multiple cancer types, such as colorectal, breast, cervical, lung, hepatocellular, pancreatic, head and neck, meningiomas and more recently gliomas." (PMID 30647847, 2018). "Since TAGLN2 was down-regulated in IDH1/2 mutant gliomas, we examined our global methylation data to determine whether increased promoter methylation may account for decreased TAGLN2 expression in these tumors." (PMID 30647847, 2018). "Our findings indicate that TAGLN2 might be a significant prognostic indicator and a potential therapeutic target for human gliomas." (PMID 29110682, 2017). "However, further investigation is necessary to elucidate the mechanism of TAGLN2 regulation of FoxM1 axis in glioma." (PMID 29110682, 2017). "Altogether, these results indicated that TAGLN2 may serve as a crucial regulator of invasion and aggressiveness by inducing mesenchymal-like properties in gliomas." (PMID 29110682, 2017).
glioma (continued). "However, the precise molecular mechanisms of the cross-talk between TAGLN2 and TGFβ2 signaling in gliomas require further investigation." (PMID 29110682, 2017). "Our findings indicate that TAGLN2 exerts a role in promoting the development of human glioma." (PMID 29110682, 2017). "TAGLN2 knockdown significantly decreased the level of Fork head box M1 (FoxM1), an oncogenic transcription factor essential for cancer progression in various types of cancers including gliomas." (PMID 29110682, 2017). "(A) Quantification of TAGLN2 mRNA expression levels in gliomas in Gravendeel datasets." (PMID 29110682, 2017). "Thus, inhibiting the succinylation of TAGLN2 may be a promising strategy for the treatment of gliomas." (PMID 40867281, 2025). "Besides, Sal A treatment suppressed TAGLN2/PI3K/Akt pathway in glioma cells." (PMID 35505656, 2022). "Additionally, activation of TAGLN2/PI3K/Akt pathway in glioma cells was also detected to investigate whether Sal A could regulate TAGLN2/PI3K/Akt to manipulate the progression of glioma and TMZ resistance." (PMID 35505656, 2022). "Taken together, these results suggest that TAGLN2 may be involved in glioma progression." (PMID 30647847, 2018). "While the role of TAGLN2 in cancers has been controversial, multiple studies have shown that TAGLN2 contributes to invasion, cell proliferation, metastases, treatment resistance and poor prognosis among several cancer types, however little is known about its role in glioma biology." (PMID 30647847, 2018). "TAGLN2 might therefore be a novel prognostic biomarker in gliomas." (PMID 29110682, 2017). "Therefore, we hypothesize that TAGLN2 may promote invadopodia formation of glioma cells via competing with cofilin and suppressing actin depolymerization." (PMID 29110682, 2017). "Moreover, to uncover the potential molecular mechanisms by which TAGLN2 promote glioma development, we detect the expression change of FoxM1, an oncogenic transcriptional factor that regulates some key mediators of cell cycle progression, including CDK2, cyclin B1, cyclin D1, p21 and p27." (PMID 29110682, 2017). "Thus, TAGLN2 may contribute to invasiveness in glioma cells by promoting EMT and the formation of invadopodia in glioma cell lines." (PMID 29110682, 2017). "We therefore investigated whether TAGLN2 regulated EMT in glioma cells." (PMID 29110682, 2017). "Subsequently, western blot and immunohistochemistry were used to verify the high expression of TAGLN2 K40succ in GEC and glioma tissues." (PMID 41189171, 2025). "The occurrence of transgelin-2 (TAGLN2) dysregulation, which is highly expressed in glioma tissues and closely correlates with prognosis and tumor stage, is known to cause certain malignancies." (PMID 38315203, 2024). "Another study calculated significant prognostic values for four hub genes (EMP3, PDPN, TAGLN2, and TIMP1) related to m6A regulators, all with high expression in high-grade glioma, and further correlation to IDH status and transcriptome subtype." (PMID 36831575, 2023). "Previous research has reported that TAGLN2 and its downstream PI3K/Akt pathway play important roles in glioma development and metastasis." (PMID 35505656, 2022). "This differential regulation of TAGLN2 provides further insight into the genetic, epigenetic and oncogenic differences between IDH1/2 WT and mutant gliomas." (PMID 30647847, 2018). "Our results show that TAGLN2 significantly contributes to invasion and proliferation in IDH WT gliomas, however the mechanism remains poorly understood." (PMID 30647847, 2018). "We compared TAGLN2 gene expression levels among all grade II (n=249) and grade III (n=265) gliomas as well as GBMs (n=153) included in the TCGA database." (PMID 30647847, 2018). "To this end, by employing an mRNA and proteomics profiling approach, we identified transgelin-2 (TAGLN2) to be differentially expressed between IDH1/2 WT and mutant gliomas." (PMID 30647847, 2018).